CD4 (CD4 molecule)
Diseases named in the same sentence as CD4 in open-access papers (continued):
Sharing a sentence is not in itself a finding about the gene and the disease.
cancer (continued). "Next, CD4-expressing cells, which are integral components of adaptive anti-cancer efficacy, were depleted." (PMID 29399400, 2018). "Our findings thus provide a rationale to target CD103+CD4+ TILs and add co-stimulation to current therapies to improve the efficacy of immunotherapies and cancer vaccines." (PMID 30505306, 2018). "Gliknik Inc. developed a Trojan cancer vaccine, consisting of chemically synthetized long peptides, containing 2 or 3 CD4 and CD8 specific epitopes from either MAGE or HPV Ag, fused to the TAT CPP." (PMID 29508006, 2018). "ATX interacts with α4β1 and αvβ3 integrins, mediating CD4 T-lymphocyte migration into secondary lymphoid organs and cancer cell metastasis, respectively." (PMID 30237860, 2018). "High PD-1 expression is a hallmark of “exhausted” T cells that have experienced high levels of stimulation or reduced CD4+ T-cell help as seen during chronic infections and cancer." (PMID 30555473, 2018). "Elsewhere, TAA-specific CD4+ T-cell clones were shown to mediate HLA-II-restricted cytotoxic activity, making them attractive effectors in cancer immunotherapy." (PMID 29403496, 2018). "Immune responses, both innate (macrophages, granulocytes, mast cells, NK cells and DCs) and adaptive (B-cells, CD8+ and CD4+) play a crucial role in cancer metastasis by inhibiting the growth of tumors, in particular, by responding to disseminated disease." (PMID 30410108, 2018). "On the other hand, cancer septic animals exhibit a decrease in a subset of PD-1lo 2B4lo IL-2-secreting CD4+ T cells (i.e. Nodes 3 and 4) relative to previously healthy septic controls." (PMID 29338031, 2018). "CD8+ or CD4+T-lymphocytes can recognize cancer antigens or over-expressed self-antigens and inhibit cancer development." (PMID 29854318, 2018). "We report only two cases of NSCLC with CD4 count of 219 and 231 cells/μL, and viral load of < 40 and 21,300 copies/mL, respectively, at cancer diagnosis (both patients smoked tobacco)." (PMID 30368240, 2018). "As both CD8+ and CD4+ T cells play a significant role in tumour rejection, most of the in silico methods for cancer immunogens prediction utilize servers for T-cell epitope prediction." (PMID 29544447, 2018). "CD4+ and CD8+ T-cell epitopes are likely to be recognized by antibodies and present a valuable diagnostic platform in patients with cancer mediated by the tumor-associated antigen (TAA) NY-ESO-149–51." (PMID 30459443, 2018). "This cytokine supports a CD4 T cell/macrophage effector axis which acts as immune surveillance mechanism for MHC II-negative cancer cells." (PMID 29780381, 2018). "At cancer diagnosis, 70 patients had a CD4 count of > 200 cells/μL with a median of 273 cells/μL (IQR 125; 481), and 73 patients had undetectable HIV viral load." (PMID 30368240, 2018). "IFN-γ, secreted by CD4+ T-cells, interacts with its receptors on the cancer cell surface and induces tyrosine phosphorylation of Jak1 and Jak2." (PMID 29796172, 2018). "Lipid and bone metabolism, cancers, cardiovascular, renal, and neurological systems should be carefully monitored, particularly in children with detectable viremia and/or with CD4/CD8 ratio inversion." (PMID 30418933, 2018). "From our model analysis, we observe that, during Cancer, the ratio of CD4 and CD8 cells reaches a mean value of 2.75, that is in sharp contrast to the normal healthy individuals which show a value of 1.48." (PMID 30183728, 2018). "The nature of the immune response to cancer, surgery and anesthesia appears to be regulated by the balance of the two subsets of CD4 T helper cells, TH1 and TH2." (PMID 30229370, 2018). "The CD8+ and CD4+ subsets are the two main T cells populations and play critical roles in host defenses against cancer." (PMID 29739434, 2018). "We conclude that cancer septic animals exhibit an increase in a subset of 2B4+ PD-1lo TNF-secreting CD4+ T cells (i.e. Nodes 1 and 2) relative to previously healthy septic controls." (PMID 29338031, 2018).
cancer (continued). "On the other hand, the value of CD4:Treg ratio in Cancer shows a value of 15.2 that is higher than the ratio observed in the normal scenario." (PMID 30183728, 2018). "Adoptive transfer and vaccination strategies to treat cancer have demonstrated that CD4+ T cell help, through co-stimulation, is required for optimal cytotoxic CD8+ T cell responses in tumors." (PMID 30505306, 2018). "The Th9 fate is characterized by the secretion of IL-9 by CD4+ T cells, leading to several pro-inflammatory and anti-cancer effects." (PMID 29891791, 2018). "Multivariable longitudinal analysis odds of cancer diagnosis as a function of age, sex, CD4+ counts, SIV and gammaherpesvirus viral loads." (PMID 30001436, 2018). "To test this, we interrogated the differences in both immunologic phenotype and function of CD4+ T cell populations in cancer septic animals as compared to previously healthy septic hosts." (PMID 29338031, 2018). "In two cases who underwent surgery in our study, infiltration of CD4+ or CD8+ cells was well detected in the area nearby the residual cancer cells." (PMID 29801474, 2018). "Although the majority of adoptive T cell therapy studies focus on cytotoxic CD8+ T lymphocytes, re-educated CD4+ T cells also show potential to eradicate cancer cells." (PMID 29770138, 2018). "This CD4-mediated CD40-dependent licensing of DCs as a precondition for functional CTLs has also been shown in vitro for human cancers." (PMID 29032503, 2018). "Duration of cART, CD4 cell count nadir below 200/mm3 and duration of HCV infection tended to be associated with an increasing risk of NANL cancers while CD8 cells count tended to be associated with a decreasing risk." (PMID 30562358, 2018). "Previous studies indicated that, activation of CD4+ T cells are required for immunization of CD8+ T cells against cancer." (PMID 29954326, 2018). "This possibility is further supported by the finding of increased TNF secretion by CD4+ T cells in cancer septic as compared to previously healthy septic hosts." (PMID 29338031, 2018). "Firstly, our results indicated that iCCA cells induce apoptosis in the primary effectors against cancer cells such as T-cells (CD4+, CD8+) and CD56+ NK cells." (PMID 29089545, 2017). "By sorting CD45RA+ naïve CD4 T cells in this study, our data reveal that a variety of cancers are able to directly mediate the differentiation of induced Treg from naïve human CD4 T cells." (PMID 28239749, 2017). "Previous studies have highlighted the role of PD-1 expression on CD8 and regulatory T cells in chronic infection and cancer, but few studies have investigated PD-1+ CD4 effector T cells." (PMID 28880903, 2017). "It is also known that a subset (5%–15%) of CD4+ T-cells can act as regulatory cells (Treg), which specifically in the context of cancer unfortunately promotes cancer growth." (PMID 28304339, 2017). "T helper cells (Th cells), which are also known as CD4+ T cells, play a central role in orchestrating the immune response to cancers." (PMID 28768490, 2017). "As CD8+ T cells the CAR redirected CD4+CD25− T cells can be likewise used as killers in the therapy of cancer in order to eliminate the cognate cancer cells." (PMID 28850063, 2017). "Cancer exosomes co-incubated with human CD4+ CD39+ Treg cells, conventional CD4+ T cells, or CD8+ T lymphocytes differentially regulated the expression of key immune function-related genes." (PMID 28101591, 2017). "Taken together, our results showed that telomerase inhibition in cancer Jurkat cells and normal CD4+ T lymphocytes due to the long‐term exposure to RrA induced telomere shortening and eventual growth arrest and apoptosis in vitro." (PMID 28984046, 2017). "We detected a significantly higher rate of PD-1 and CTLA-4 expression on TILs compared to PBMC of cancer patients with highly variable expression profiles on CD4+ and CD8+ cells." (PMID 28574843, 2017).
cancer (continued). "CD4+ T cells are of particular interest for the use in adoptive cell therapy of cancer because they differentiate into various cell subsets which initiate, modulate, or suppress a cellular and humoral immune response." (PMID 28850063, 2017). "We and others have previously shown that strong immunostimulatory therapies for cancer induce potent proliferation of memory (CD44high) CD4 and CD8 T cells in the spleen and lymph nodes." (PMID 28428882, 2017). "CD4+ NKG2D+ T cells with regulatory function were found in both MICA+ cancer patients 18 and juvenile‐onset systemic lupus patients." (PMID 28224733, 2017). "Since the high expression of CD4+ T lymphocytes and CD8+ T lymphocytes was associated with better outcomes of cancer patients, the PD-L1 expression in TIICs was possibly associated with better cancer prognosis." (PMID 28453554, 2017). "Regulatory T cells (Tregs), a subset of immunosuppressive Foxp3+CD25+CD4+ T cells that play an important role in maintaining self-tolerance, are enriched in many cancers." (PMID 28290464, 2017). "The aim of this study was to define the effect of short‐term and long‐term RrA exposure on proliferation of cancer Jurkat cell line and normal human CD4+ T lymphocytes." (PMID 28984046, 2017). "Cancer cells have the ability to promote expansion of CD4 Tregs population, which in turn, due to FasL/CD95L expression, are able to stimulate apoptosis in effector T lymphocytes via CD95-dependent pathway." (PMID 29075318, 2017). "IL-2/IL-2R signaling has contradictory immunomodulatory effects, since it not only facilitates proliferation of cytotoxic CD8 T cells that kill cancer cells, but also suppresses the immune response by promoting inhibitory CD4+ Treg cells." (PMID 28545581, 2017). "Since the adjuvant effects of IL-7 in enhancing cancer vaccine-induced T-cell responses have recently been demonstrated, we posit that the IL-7Rα+ polyfunctional CD4+ effector cells arising after ACT would be amenable to adjuvant IL-7." (PMID 28939858, 2017). "The cell death occurring in PBMCs co-cultured with cancer cells was evaluated through FACS analysis by examining CD4+, CD8+ T-cell and CD56+ NK cell populations." (PMID 29089545, 2017). "In this study, we have investigated the ability of IL-21 to inhibit FOXP3 induction in purified naïve CD4 T cells in the context of culture supernatants from a number of cancer cell lines." (PMID 28239749, 2017). "This difference is not expected to be due to an error from sample preparation and analysis because the same analysis of other cancer types demonstrated higher expression of CD8 transcripts then CD4." (PMID 29163521, 2017). "We investigated the levels of telomerase activity in RrA‐exposed cells, and an unexpected finding was the small difference in hTERT expression and telomerase activity between cancer Jurkat cells and normal activated CD4+ T lymphocytes." (PMID 28984046, 2017). "Collectively, these findings identify CD4+ T cell subsets with properties critical for improving cancer immunotherapy." (PMID 29213079, 2017). "Here, the authors show that CD26 identifies three CD4+ T cell subsets with distinct immunological properties in both healthy individuals and cancer patients." (PMID 29213079, 2017). "Change in FEV1 during the 11-year follow-up period was associated with blood DNA methylation level in TRIM27 gene (p value = 1.55 × 10−6), a negative regulator of CD4 T cells, and also involved in cancer development." (PMID 29299071, 2017). "Significantly more naive CD4+ T cells adhered to all the cancer samples, even those with the least numbers of CCL18+ TAMs, compared to the DCIS samples." (PMID 28290464, 2017). "The AUC values were calculated for each T-cell subpopulation (all T cells, cytotoxic T cells, CD4+ Teff, Treg and other T cells) within a 20 μm radius of cytokeratin 8+ cancer cells." (PMID 28447602, 2017). "The first evidence supporting CD4+ T cell dependent rejection of cancer cells came from melanoma models." (PMID 28798348, 2017).
cancer (continued). "We observed a strong nuclear staining for Foxp3 in lymphocytes and cancer cells and strong membranous/cytoplasmatic reaction for CD4 and CD8, but low for CD25 and CTLA-4." (PMID 28831395, 2017). "For example, a vast amount of data has been amassed presenting opportunities for the use of CD4 Tregs as direct targets for new targeted agents with consideration of the features of Treg biology in different human cancers." (PMID 29075318, 2017). "The variables include dendritic and cancer cells, CD4+ and CD8+ T cells, IL-12 and IL-2, GM-CSF produced by the vaccine, and a T cell checkpoint inhibitor associated with PD-1." (PMID 28542574, 2017). "The mathematical model is represented by a system of partial differential equations, based on the interactions among cancer cells, dendritic cells, CD4+ and CD8+ T cells, cytokines IL-12 and IL-2, GM-CSF, PD-1, PD-L1, PD-1-PD-L1 complex and anti-PD-1." (PMID 28542574, 2017). "Serum sIL-2R and the number of CD4+ Tregs were reported to display a positive correlation in cancer patients." (PMID 28545581, 2017). "Our previous studies have shown that treatment with systemic immunostimulatory therapies for cancer results in preferential induction of apoptosis in the CD4 T cell population in an IFNg-dependent mechanism." (PMID 28428882, 2017). "Data from patients suffering from a wide range of cancer types has further indicated that there appears to be a positive correlation between increased number of intra-tumoral FoxP3-expressing CD4+ T cells and poor prognosis for cancer patients." (PMID 28970798, 2017). "In general, our data indicated that excessive Wnt signaling weakened anti-cancer reaction of CD4+ T cells, and favored CRC graft growth." (PMID 28147310, 2017). "In order to focus on the combination therapy of the two drugs, we consider in the model only the following variables: cancer cells (C), dendritic cells (DCs), CD4+ and CD8+ T cells, GM-CSF, PD-1, PD-L1, PD-1-PD-L1 complex, and cytokines IL-12 and IL-2." (PMID 28542574, 2017). "Attenuated Listeria monocytogenes (L. monocytogenes, LM) induces specific CD8+ and CD4+ T cell responses, and has been identified as a promising cancer vaccine vector." (PMID 28706878, 2017). "The respective and the joint effects of secreted gelsolin and cancer cells on CD4+ and CD8+ T lymphocytes suggested that surface markers were involved in a cell-to-cell interaction." (PMID 29100377, 2017). "Eighty-five percent (664/781) of isolated Tcc were positive for CD4 with a similar distribution on the evaluated cancer tissues: 264, 220, and 180 from CT, MT, and HM, respectively." (PMID 29375559, 2017). "We recently corroborated this conclusion by engineering OMVs with seven additional cancer CD4+/CD8+ T cell epitopes and by demonstrating the induction by all seven engineered OMVs of epitope-specific T cell responses (manuscript in preparation)." (PMID 29164053, 2017). "CD4+ Treg cells are well characterized whereas the role of CD8+ Tregs in cancer has recently started to crease attention." (PMID 28487507, 2017). "In our case, although few infiltrating CD8+ T cells were observed, large numbers of CD4+ T cells were present along the cancer stroma in both biopsy and excised specimens and dissected lymph nodes." (PMID 28488173, 2017). "The balance between immune effector CD4+ or CD8+ T cells and immune suppressive Tregs is critical for either protective or pathogenic immune response, hence determining the outcome of cancer treatment." (PMID 28807056, 2017). "Despite a clear increase in the total number of T lymphocytes in carcinoma tissue, it has been shown that the relative proportions of CD4+ and CD8+ T lymphocytes remain the same." (PMID 29020986, 2017). "There was a significantly higher frequency of CD8+ T- lymphocytes (15 cases) than of CD4+ T- lymphocytes (5 cases) in cancer nests." (PMID 27689405, 2016). "The major cell populations for cellular immunity against cancer include CD4+ T helper (Th) and CD8+ T lymphocytes." (PMID 26828466, 2016).
cancer (continued). "Further, the effect of MEK inhibitors on CD4+ T cells raises questions about the immunosuppressive effects of using MEK inhibitors in cancer treatment, especially as current clinical trials combine MEK inhibitors with checkpoint-blockade inhibitors." (PMID 27376549, 2016). "The cancer patient 2-derived CD4+ T cell lines that were harvested from the induction culture responded to the CDCA139-764, CDCA155-78, and LY6K172-191 peptides in an HLA-DQ or HLA-DR-restricted manner." (PMID 27050553, 2016). "Nevertheless, CLL Mo-DCs induced higher frequency of Tregs (CD4+CD127lowCD25hiFOXP3+), which has been seen in other cancer types." (PMID 27317770, 2016). "Th17 cells are a newly found subset of distinct CD4+ Th effector cells' family and are found to play an important role in cancers." (PMID 27722177, 2016). "PD-1 and PD-L1 cancer cell and TILs expressions were further investigated as to their relationship to the CD4+ and CD8+ T cell population when we grouped cancer cell expression in four groups." (PMID 26625204, 2016). "When the immunologic function in patients with cancer is impaired, CD4+ cells will decrease, CD8+ cells will increase, and the CD4+/CD8+ ratio decreases or even inverts." (PMID 27738441, 2016). "These include Tregs and Th17s, CD4+ T cells which have been observed to mechanistically promote tumorigenesis, cancer progression and metastasis through immunosuppressive and pro-inflammatory functions." (PMID 27784305, 2016). "In vitro stimulation of peripheral blood T cells with CD14-ML-DC that were loaded with cancer antigen-derived peptides led to the establishment of CD4+ and CD8+ T cell lines that recognized the peptides." (PMID 27050553, 2016). "Cancer septic mice had a decrease in both the frequency and absolute numbers of splenic CD4+ lymphocytes compared to previously healthy septic mice." (PMID 27018973, 2016). "Several recent clinical trials have shown that depletion of CCR4-expressing FoxP3+CD4+ Treg cells by anti-human CCR4 monoclonal antibody is a promising approach to augment antitumor immune responses in cancer patients." (PMID 27177223, 2016). "Administration of daclizumab in conjunction with cancer vaccine was associated with prolonged Treg depletion in peripheral blood and priming of CD8 and CD4 responses to vaccine antigens." (PMID 27330808, 2016). "Given the key role of CD4+ T cells as orchestrators of adaptive immune responses, there is increasing interest in the use of this T cell subset in immunotherapy against cancer." (PMID 27626487, 2016). "Major shifts in intestinal commensal bacteria often result in changes in CD4+ T lymphocyte populations, leading to an influx of Th17 cells, chronic inflammation, and eventually cancer." (PMID 31456935, 2016). "The findings of this study provide valuable data for further research into in vitro expansion of CD4+ Th1-like cells, with potential applications to cancer treatment involving ACT." (PMID 27588200, 2016). "We have also reported that the expression of costimulatory ligands CD80 and 4-1BBL on murine CD4 T-cells prolonged their longevity in vitro and in vivo, indicating their potential for use as alternative APCs for cancer immunotherapy." (PMID 27323820, 2016). "CD4+ cell expression of the Th1 marker CXCR3 was increased in cancer septic mice, while expression of the Th2 marker CCR4 was not different between previously healthy septic mice and cancer septic mice." (PMID 27018973, 2016). "Intriguingly, MFIs of BTLA or CTLA-4 on CD4+ T cells from cancer patients were significantly higher than that from normal donors." (PMID 27577071, 2016). "MHC class II (MHCII) molecules function to present antigen to CD4 T lymphocytes generating helper T cell responses that are critical for effective adaptive immune responses against infection and cancer." (PMID 27729860, 2016).